VEGFA (vascular endothelial growth factor A)
Diseases named in the same sentence as VEGFA in open-access papers (continued):
Sharing a sentence is not in itself a finding about the gene and the disease.
tumor (continued). "We found that CD276 and VEGFA expression was significantly positively correlated with the expression of OTUD6B in nearly all types of cancer, so were the immune checkpoint inhibitor genes HMGB1 and TLR4, suggesting that OTUD6B may provide some help for tumor immunotherapy through these targets." (PMID 36052059, 2022). "However, it is reported that bevacizumab from tumour‐derived EVs could not bind to VEGFA, so there is a possibility that tumour cells escape themselves from treatment by bevacizumab shedding at the surface of tumour‐derived EVs." (PMID 33586248, 2021). "Finally, the study revealed that the genetic depletion of hypoxia-induced CA IX expression by MDA-MB-231 LM2-4Luc+ cells in vitro leads to reduced levels of VEGFA, which may contribute to the observed effects of SLC-0111 on the normalization of tumor vasculature." (PMID 34948200, 2021). "The present study aims to compare the full spectrum of VEGFA isoforms expressed in paired HCC and non-tumorous (NT) liver samples and to quantitatively evaluate changes in the expression of major isoforms and their association with tumor clinicopathological characteristics." (PMID 29888133, 2018). "We speculate that pre-angiogenic tumor tissues, which do not harbor the VEGFA gene copy number amplification and therefore express low levels of VEGFA, send signals to the bone marrow and/or the blood circulation that lead to the recruitment of the macrophages." (PMID 28403223, 2017). "Collectively, these data suggest that miR-497 may regulate proliferation, survival and tumor vascular permeability by targeting key genes involved in DDR such as WEE1 and CHEK1, cell growth and viability such as AKT3 and BCL2 and angiogenesis regulators such as VEGFA." (PMID 26824183, 2016). "Furthermore, restoration of Nrf2 function in transformed cells decreased reactive oxygen species and impaired in vivo tumor growth (P = 0.001) by mechanisms that included sensitization to apoptosis, and a decreased hypoxic/angiogenic response through HIF-1α destabilization and VEGFA repression." (PMID 24491031, 2014). "The importance of FLT1, PGF, VEGFA and VEGFB expression and their functions in MLS/RCLS tumor development remain unclear but our results point out this receptor/ligand system as operational in MLS/RCLS and as such a potential target for intervention in this tumor type." (PMID 20515481, 2010). "Consistent with this, we found all angiogenesis-related genes to be significantly upregulated in non-pCR patients, with VEGFA, CXCL8, CXCL2, CXCL3, and HBEGF identified as core drivers of tumor angiogenesis and immune escape." (PMID 41514936, 2026). "These lipifibrogenesis are not inert bystanders; they actively secrete vascular endothelial growth factor A (VEGFA), directly contributing to tumour angiogenesis." (PMID 41469334, 2026). "Although during inflammatory lymphatic remodeling the production of VEGFA and VEGFC is expected by activated macrophages, there was no observable increase of either within the treated tumor." (PMID 39998766, 2025). "Both tumour and nontumour cells in the tumour ecosystem produce factors such as HIF, VEGFA (Vascular Endothelial Growth Factor), IL-6, and IL-8, which stimulate endothelial cell proliferation and thus tumour vascularisation." (PMID 41009413, 2025). "In addition, we verified other NF-κB downstream genes (VEGFA, TNFα, and uPA) which involved in the regulation of tumor microenvironment and found that GATA4 can also down-regulate their mRNA levels, suggesting that GATA4 may be a potential factor in the regulation of tumor microenvironment." (PMID 38653973, 2024).
tumor (continued). "This induces mitostatin-dependent mitophagy, which leads to negative feedback regulation of vascular endothelial growth factor A (VEGF-A) production, thereby attenuating tumor angiogenesis." (PMID 37237941, 2023). "Hsa-miR-101-3p targeting VEGFA showed a negative correlation with hypoxia scores across most cancers, including LUAD and LUSC, suggesting its role as a tumor suppressor." (PMID 37852616, 2023). "A strong association between SF3B1 expression and key tumor -markers of development/progression (VEGFA/MKI67/EGFR/CDK4/PDGFRA) was found in GBM (CGGA- and Rembrandt-datasets), but not in the non-tumor samples (Rembrandt-dataset)." (PMID 35086552, 2022). "In glioma, suppression of PELP1 can down-regulate the expression of VEGFA, but no further studies have been conducted, which suggests that PELP1 has a potential role in regulating tumor angiogenesis." (PMID 35053547, 2022). "Apparently, the micro-vessel density and VEGFA+ cells were decreased in the R848 group and the RFA+R848 group, while RFA+R848 did not further reduce the tumor micro-vessels compared with R848 monotherapy." (PMID 35719978, 2022). "In the VEGFA-amplified PDTX model of OSA, sorafenib resulted in reduced tumor volume compared to vehicle, whereas in another PDTX model without VEGFA-amplified OSA, there was no benefit from sorafenib treatment." (PMID 36012610, 2022). "S100A4+ MAFs promote angiogenic microenvironment establishment in support of metastatic colonization by providing vascular endothelial growth factor-A (VEGF-A), while the ablation of S100A4+ CAFs does not affect angiogenesis at the primary tumor site." (PMID 34112258, 2021). "The anti-tumor and anti-angiogenic effect displayed by ADAMTS1 has been described also in the context of GC, where a negative correlation between ADAMTS1 and VEGFA mRNA and protein expression was detected." (PMID 32456248, 2020). "TTP has been shown to downregulate several well-established markers for tumor progression like BCL2, VEGFA, and MYC in non-liver tissue." (PMID 31717307, 2019). "In a xenograft model, vascular endothelial growth factor A (VEGFA) recruited monocytes that differentiated into TAMs in the presence of IL-4 and the absence of these TAMs inhibited tumor growth, invasion, proliferation, and angiogenesis." (PMID 28241846, 2017). "In PTSMT, HGF, THBS1 and VEGFA are all expressed at low levels, indicating that HGF signalling does not contribute significantly to tumour angiogenesis." (PMID 24398114, 2014). "Therefore, the overexpression of VEGFA and hypoxia-induced genes in non-responders to radiation therapy in our cohort supports the use of therapies that combine anti-angiogenics with radiation therapy to enhance the efficacy of radiotherapy by reducing tumor hypoxia." (PMID 20822523, 2010). "While these factors are known to mediate pro-angiogenic and tumor-promoting processes in the TME (e.g., IL-6 and IL-8 can upregulate VEGFA expression in tumor cells to drive angiogenesis), analysis of 22Rv1 tumor cells under huB12-MMAE treatment showed no change in VEGFA expression." (PMID 41154598, 2025). "Indeed, the administration of CAR T cells and anti-VEGFA antibody significantly prolonged survival and reduced GPR65 KO tumor burden compared with mice receiving isotype control (no anti-VEGFA)." (PMID 39998425, 2025). "Tumor or VEGF-induced zippering of lymphatic junction was not affected in a VEGFR2 mutant mouse model (Vegfr2Y949F/Y949F) which lacks the Y949 residue critical for activation of SFKs in response to VEGFA." (PMID 38148112, 2024). "Moreover, BRAFi significantly decreased the expression of HIF‐1α in D4M tumors, and the effect was maintained in combination with anti‐m‐VEGFA treatment but not after anti‐mVEGFA alone, indicating that BRAF inhibition is critical for abrogating tumor hypoxia." (PMID 37183363, 2023).
tumor (continued). "By comparing metastasis-related genes expressed in paired nontumor tissue– and tumor tissue–purified monocytes, we found that levels of MMP9, VEGFA, and CCL8 were all increased in the tumor monocytes compared with the nontumor monocytes, with CCL8 exhibiting the most marked upregulation." (PMID 35362480, 2022). "The data obtained from these tumours are also consistent with an upregulation of anti-angiogenic ING4 mRNA levels in the human xenograft tumours in vivo, with no significant changes are detected for ANG, VEGFA, HIF1α, THBS2 and COL18A1." (PMID 35513564, 2022). "However, analysis in SQC showed no significance between the VEGFA mRNA expression and TNM stage, tumor size." (PMID 31892982, 2020). "Moreover, probes targeting VEGFA, GRPR, and αvβ3 showed positive signal in normal tissue and false-negative tumor detection in early-phase clinical trials." (PMID 32990883, 2020). "Treatment of MCF7 cells with VEGFA at low and high concentrations (0.5 and 10 ng/mL) did not modify miR-20a expression, thereby suggesting that miR-20a expression is not related to VEFGA levels in the tumor environment." (PMID 29617404, 2018). "Our C-G2P experiments suggested that VEGFA and mtCTNNB1 mediate opposing epistasis effects relevant to CCA development within the genetically heterogenous tumour ecosystems analysed, as nodules of this tumour class were consistently negative for mtCTNNB1 and positive for VEGFA." (PMID 40721510, 2026). "However, while angiogenesis is dependent on pro-angiogenic factors, such as VEGFA, secreted in the TME, VM formation is independent of these factors, as network formation is not enhanced in the presence of either normoxic or hypoxic tumor-conditioned medium." (PMID 41009691, 2025). "Furthermore, the clinical correlations showed that the higher level of VEGFA or MVD has a positive correlation with the expression of CEBPD and a negative relation to hsa-miR-429 and leads to tumor aggressiveness with worse disease-specific, metastasis-free survival in UBUC and UTUC cohorts." (PMID 35203290, 2022). "Interestingly, when compared to their individual tumor of origin and not as a cohort, primary cell cultures displayed an even slightly higher mRNA expression of CA9 and HIF1A, while the expression of VHL, VEGFA and VEGFC remained constant." (PMID 35646693, 2022). "However, based on RNA-seq analysis of HCT-116 cells, the level of only VEGFA was slightly increased upon knockdown of HHEX (FC = 1.5), and none of the other HHEX target genes involved in the tumor-suppressive function of HHEX were expressed in CRC cells (GSE196333)." (PMID 36008411, 2022). "Furthermore, ZNF281 in CAFs upregulated CCL2 and CCL5 rather than VEGFA expression, which stimulated angiogenesis and vascular permeability through P38 MAPK signaling in endothelial cells, consequently contributing to lung PMN formation in tumor metastasis." (PMID 36438499, 2022). "Notably, not limiting to VEGFA, majority of pro-angiogenesis factors can interact with VEGFR2 and by such mechanism, it functions as the molecular hub responsible for the integration of pro-angiogenic signals in tumor microenvironment." (PMID 29403376, 2017). "However, prior evidence also suggests that different blood vessel subtypes in the tumor microenvironment do not all respond homogeneously to anti-VEGF treatment, inferring the presence of contextual factors promoting heterogeneity in VEGFA expression and activity." (PMID 33927723, 2021). "Interestingly, the increased VEGFA expression significantly correlated with both decreased levels of activated CD8+ T cells and Th1 cell infiltration in the high immune infiltration tumor microenvironment but not in the low immune infiltration tumor microenvironment." (PMID 31620363, 2019).
cancer (7,485 papers, 1996 to 2026). A tumor composed of atypical neoplastic, often pleomorphic cells that invade other tissues. "VEGFA-perturbed nodules also exhibited a greater abundance of cancer-associated fibroblasts compared with nodules with mtCtnnb1, indicating that genetic alterations also shape, and possibly co-opt, their TME." (PMID 40721510, 2026). "VEGF-A (encoded by VEGFA) not only drives angiogenesis but also contributes to immune evasion and metastasis, making it a key target in cancer research." (PMID 41514658, 2025). "The green cluster—containing VEGFA, miR-200c-3p, and miR-141-3p—is associated with angiogenesis, with dysregulated angiogenesis being a hallmark of cancer." (PMID 39910456, 2025). "VEGFA and impaired DC population is correlated in cancer patients and anti-VEGFA treatment is associated with decrease in accumulation of immature DC cells." (PMID 39985645, 2025). "Fibroblast S8 cells exhibited high expression of HIF1A and VEGFA, suggesting similarity to hypoxia‐associated cancer‐associated fibroblasts (CAFs)." (PMID 40432877, 2025). "For instance, miR-101-3p downregulation in cancer-associated fibroblasts (CAFs) increases vascular endothelial growth factor A (VEGFA) secretion, promoting LC metastasis via the Akt/eNOS pathway." (PMID 39712244, 2024). "In summary, in the present study, we explored the reciprocal interaction between TNBC cells and TAMs mediated by VEGFA and further clarified the role and underlying mechanisms of VEGFA in regulating cancer stemness." (PMID 38169627, 2024). "Once located on the blood vessel, migrating TAMs differentiate into perivascular Tie2-expressing macrophages that mediate cancer cell intravasation by expressing VEGFA and causing vascular leakage." (PMID 39003350, 2024). "KEGG enrichment analysis identified crucial nodes in the signaling pathways associated with cancer development, including VEGFA, INS, IGF1R, and INSR." (PMID 38305809, 2024). "Elevated VEGFA levels are associated with increased angiogenesis and consequently, a higher risk of cancer progression." (PMID 39337657, 2024). "Our results showed that the expression level of VEGFA was correlated with immune cell infiltration, including M2 TAMs and Tregs, which were associated with promoting cancer progression." (PMID 36729917, 2023). "Among them, VEGFA is a key mediator of cancer-associated neo-angiogenesis and progression which have been explored extensively for cancer therapy." (PMID 37115092, 2023). "In the present study, our interest was focused on three SNPs in the promoter region of the VEGFA gene, −460 T/C, −2578 C/A, and −2549 I/D, widely reported to be associated with many cancer developments and progressions." (PMID 37189572, 2023). "Many factors are associated with cancer pathogenesis, including vascular endothelial growth factor-A (VEGFA) and circular RNAs (circRNA)." (PMID 37234708, 2023). "This was related to the enhanced proliferation of cancer-associated fibroblasts and increased expression of vascular endothelial growth factor A (VEGF-A)." (PMID 37298790, 2023). "The patterns of 3 differentially expressed immune-associated CRGs, MAP2K2, SOD1, and VEGFA, in 3 single-cell samples of normal tissues adjacent to cancer were further analyzed as controls." (PMID 37822927, 2023). "Activation of the VEGFA-VEGFR2 pathway is commonly observed in many types of cancer and is associated with poor prognosis." (PMID 37908231, 2023). "The VEGFA gene is considered a hallmark in cancer-related studies because of its role in angiogenesis, accomplished periodically from pre-existing vascular networks." (PMID 37081847, 2023). "Recently, there are growing number of studies addressing the association between VEGFA gene SNPs and various cancer types, including urogenital carcinomas and lung cancer." (PMID 37189572, 2023). "In cohort 2, HIF-1α, TIMP-1, VEGFA, and Ki-67 expression of surgical lung biopsy cases was representatively increased in the cancer cells underlying IP." (PMID 38012636, 2023).
cancer (continued). "The pathway description indicated the VEGFA gene is implicated in various signalling pathways in cancer, a main inducer of blood vessel growth and an important growth factor for epithelial cells." (PMID 37048688, 2023). "VEGFA promoter polymorphism −2578C/A (rs699947) is widely studied in a large number of angiogenesis-associated diseases, including many different types of cancers and their response to anti-VEGFA agent treatment." (PMID 35326447, 2022). "VEGFA/VEGFR2 or VEGFA pathway alone is associated with T-regs promoting angiogenesis in a variety of cancers." (PMID 36158681, 2022). "The continuous use of antibodies leads to high costs, and the blockade of VEGFA in non-cancer nests causes side effects, such as gastrointestinal perforation and proteinuria." (PMID 35626012, 2022). "MiR-206 prevents the suppression of tumor angiogenesis, both in vivo and in vitro, by inhibiting the 14-3-3z/STAT3/HIF-1α/VEGF signaling pathway and preventing normal fibroblast to cancer-associated fibroblast conversion by downregulating VEGFA expression." (PMID 35885514, 2022). "Other data suggest a discordance between VEGFA expression and VEGFA plasma and that the other genes involved in VEGFA signaling are also important in cancer susceptibility and phenotype." (PMID 34440447, 2021). "Angiogenesis, a hallmark of cancer, is induced by vascular endothelial growth factor–A (hereafter VEGF)." (PMID 34673569, 2021). "The rs10434 polymorphism, which is located in the 3′UTR region of VEGFA, has been widely studied in association with carcinoma and pregnancy loss." (PMID 34200782, 2021). "An indirect increase of VEGFA occurs via the recruitment of cancer associated fibroblasts (CAFs) prompted by the upregulation of laminin α1, which can also bind the cytokine, further enhancing the pro-angiogenic response." (PMID 32456248, 2020). "VEGFA then acts as the mediator that confers to ID4 protein in cancer cells the ability to cause ID4 induction in macrophages." (PMID 32054109, 2020). "The core-clock genes NR1D1, PER3, CSNK2A1, and the cancer associated gene VEGFA showed statistically significant results in our Cox-regression based survival plots (log rank test p ≤ 0.05)." (PMID 32295075, 2020). "LMα1 engages an intimate crosstalk between cancer, stromal, and endothelial cells through the recruitment of cancer-associated fibroblasts (CAFs) and the induction of VEGFA production via the integrin α2β1-CXCR4 (C-X-C chemokine receptor type 4) complex." (PMID 32456248, 2020). "Aberrant VEGFA expression has been reported to be linked to poor clinical prognosis and metastasis in numerous cancer types." (PMID 32896063, 2020). "In some tumours, the expression of VEGFA is associated with angiogenesis and metastasis, which are processes involved in the invasion of cancer cells using the extracellular matrix (ECM)." (PMID 33228670, 2020). "VEGFA, encoding vascular endothelial growth factor A, is observably related to the initiation and progression of cancer." (PMID 31950034, 2019). "VEGFA is one of the best studied angiogenic factors, and variants have been associated with increased risk of a variety of cancers, including BrCa." (PMID 30651598, 2019). "VEGFA, which was selected as a target gene of miR-150-5p, is closely associated with metastasis and angiogenesis of human cancers." (PMID 30476901, 2018). "Current studies of the role of VEGFA splice variants in cancer development are mainly focused on balance of pro- and anti-angiogenic VEGFA isoform groups." (PMID 29888133, 2018). "This study is the first to identify a common variant near the VEGFA gene regulating the plasma levels of the protein in cancer patients." (PMID 30397360, 2018). "VEGFA which was selected as a target gene of miR-150-5p have been reported to be closely associated with metastasis and angiogenesis of human cancers." (PMID 30250022, 2018). "Our study points out VEGFA as an important player in GCNT3-associated functions in cancer and drug resistance." (PMID 29855486, 2018).